NTMT1 (N-terminal Xaa-Pro-Lys N-methyltransferase 1)
Description:
Distributive alpha-N-methyltransferase that methylates the N-terminus of target proteins containing the N-terminal motif [Ala/Gly/Pro/Ser]-Pro-Lys when the initiator Met is cleaved. Specifically catalyzes mono-, di- or tri-methylation of the exposed alpha-amino group of the Ala, Gly or Ser residue in the [Ala/Gly/Ser]- Pro-Lys motif and mono- or di-methylation of Pro in the Pro-Pro-Lys motif. Some of the substrates may be primed by NTMT2-mediated monomethylation. Catalyzes the trimethylation of the N-terminal Gly in CENPA (after removal of Met-1). Responsible for the N-terminal methylation of KLHL31, MYL2, MYL3, RB1, RCC1, RPL23A and SET. Required during mitosis for normal bipolar spindle formation and chromosome segregation via its action on RCC1.
Synonyms: NTM1A; C9orf32; METTL11A; NRMT; NRMT1; AD-003; HOMT1A
Tractability: Small molecule: a structure with a bound ligand is known; a high-quality ligand is known; it has a high-quality binding pocket. PROTAC: ubiquitination databases record sites on it; its protein half-life has been measured; a small molecule that binds it is known.
Target class: Enzyme; Transferase
Gene: Protein-coding gene on chromosome 9 (129,606,704 to 129,636,744, forward strand). Ensembl gene ENSG00000148335.
Subcellular location: Nucleus
Subcellular location (Human Protein Atlas): Nucleoplasm; Cytosol
Gene Ontology:
Molecular function: histone methyltransferase activity; N-terminal protein N-methyltransferase activity; protein binding; protein methyltransferase activity; methyltransferase activity
Biological process: chromosome segregation; N-terminal peptidyl-glycine methylation; N-terminal peptidyl-proline dimethylation; N-terminal peptidyl-serine dimethylation; N-terminal peptidyl-serine trimethylation; spindle organization; chromatin remodeling
Cellular component: cytosol; nucleoplasm; nucleus; cytoplasm
Genetic constraint (gnomAD): Loss-of-function variants: 8 observed, 18.14 expected, observed/expected ratio (o/e) 0.44, 90% interval 0.26 to 0.8. The upper end of that interval is the gene's LOEUF score, 0.8, which puts it in group 3 of 6, group 1 being the genes least tolerant of losing a copy. Missense variants: 221 observed, 317.68 expected, observed/expected ratio (o/e) 0.7, 90% interval 0.62 to 0.78. Synonymous variants: 128 observed, 133.34 expected, observed/expected ratio (o/e) 0.96, 90% interval 0.83 to 1.11.
Homologues: Orthologues: macaque NTMT1 (100% identical), chimpanzee NTMT1 (99% identical), mouse Ntmt1 (94% identical), rat Ntmt1 (94% identical), dog NTMT1 (92% identical), pig NTMT1 (92% identical), guinea pig NTMT1 (88% identical), tropical clawed frog ntmt1 (74% identical), zebrafish ntmt1 (72% identical), Drosophila melanogaster Ntmt (42% identical), Caenorhabditis elegans homt-1 (39% identical). Paralogues in human: NTMT2 (51% identical).